MET (MET proto-oncogene, receptor tyrosine kinase)
Diseases named in the same sentence as MET in open-access papers (continued):
Sharing a sentence is not in itself a finding about the gene and the disease.
lung adenocarcinoma (continued). "For instance, Fu and collaborators reported on a case of lung adenocarcinoma, stage IIIA-N2, positive for a MET exon 14 skipping alteration treated by savolitinib, a MET TKI, in the neoadjuvant setting." (PMID 38611088, 2024). "Prof. Masayuki Noguchi’s team identified that SFN specifically binds to ubiquitinated protease 8 (USP8) in lung adenocarcinoma cells, enhancing the stabilization of receptor tyrosine kinases (RTKs), including EGFR and MET, through abnormal regulation of USP8." (PMID 37398672, 2023). "Another patient with lung adenocarcinoma showed MET amplification on re-biopsy after HPD and remission occurred with a c-MET inhibitor." (PMID 35582541, 2022). "MiRNA hsa-mir-30a and lncRNA AC104472.1 constituted regulatory module for lung adenocarcinoma a with TPI1, KPNA2, MET, HSP90B1, P4HB, DSP, CDH1, and ENO1." (PMID 36138770, 2022). "A study demonstrated that the lncRNA LOC389641 played an oncogenic role in lung adenocarcinoma through suppressing autophagy by reducing the expression of autophagy-related proteins, p-AMPK and LC3B via EGFR/MET/STAT3 signalling." (PMID 35379783, 2022). "The survival analysis shows that the prognosis of some tumors was significantly correlated with HGF/c-MET expression, including HNSC, lung adenocarcinoma (LUAD) and pancreatic adenocarcinoma (PAAD)." (PMID 34261467, 2021). "Of 516 lung adenocarcinoma (LUAD) cases, 18 (3.5%) had MET and 9 (1.7%) FAM3C CN amplification, 8 deriving from the MET amplification group." (PMID 33596971, 2021). "Western blot analysis and COX enzymatic assay showed significant reduction in the total and activated c-MET levels and inhibition of COX1/2 activity in the lung adenocarcinoma cells A549 and NCI-H322M, in vitro." (PMID 32545325, 2020). "c-MET and PTGS2 proved highly expressed in several patient lung adenocarcinoma samples, along with several other tumor types in cBioPortal database." (PMID 32545325, 2020). "We used two platforms for CTC capture, and assessed MET expression in CTCs and matched-bronchial biopsies in patients with advanced-stage III/IV lung adenocarcinoma." (PMID 28212540, 2017). "Taken together, our study demonstrated that miR-206 overexpression in human lung adenocarcinoma cisplatin resistant cells inhibited the EMT and cisplatin resistance by targeting MET and suppressing its downstream PI3K/AKT/mTOR signaling pathway." (PMID 27014910, 2016). "It will be important to clarify the relationship of MET and EGFR with ROR1 in lung adenocarcinoma patients." (PMID 25978653, 2015). "The lung adenocarcinoma cell line, HCC827, exhibited the greatest number of activated RTK pathways, with HER1, c-MET, and HER2 being highly activated, PI3K being moderately activated, and HER3 as well as IGF-1R being lowly activated." (PMID 22091388, 2011). "Dysregulated MET signaling, such as MET overexpression or MET amplification (METamp), is a important mechanism of resistance to EGFR tyrosine kinase inhibitors (TKIs) in patients with EGFR-mutant lung adenocarcinoma (LUAD)." (PMID 40470164, 2025). "As for the other reference genes such as ROS1, HER2, RET, MET, NTRK1, NTRK2, and NTRK3, our study did not identify mutations in these genes in patients with lung adenocarcinoma." (PMID 38828424, 2024). "Additionally, protein levels of ETV5, a key player in the maintenance of Ras-induced lung adenocarcinoma in alveolar type II cells, were higher in HEK293T cells expressing METΔexon14 compared to just ectopic MET WT overexpression." (PMID 35326531, 2022). "Furthermore, promising therapeutic effects have been demonstrated on lung adenocarcinoma patient-derived xenograft (PDX) models, particularly in tumors with high expression of c-MET." (PMID 31948451, 2020).
lung adenocarcinoma (continued). "For example, MET amplification can be detected after the treatment of the first generation of EGFR-tyrosine kinase inhibitor (EGFR-TKI), gefitinib or erlotinib, in EGFR-mutant lung adenocarcinomas, and the combination of EGFR-TKI and MET inhibitor is demonstrated to be an effective treatment." (PMID 28158234, 2017). "We observed no strong positive correlations for lung adenocarcinoma, providing evidence that the transcriptional effects of mutations in KRAS, EGFR, MET, NTRK1, and PIK3CA are distinct from each other." (PMID 29322935, 2017). "Therefore, we studied the effects of BRAFV600E, MET activation, and EGFRT790M, alone or in combination, on growth and therapeutic response in human EGFR-mutant lung adenocarcinoma cellular models." (PMID 28287179, 2017). "Another 64 pan-negative lung adenocarcinomas were also stained for MET protein; 42 scored as negative, 12 scored as weak, seven as moderate, and three as strong." (PMID 27223439, 2016). "We further revealed that 1.9% (17 of 904) of non-smoking lung adenocarcinomas (NSLAD) harbored MET exon 14 skipping." (PMID 27223439, 2016). "Using FISH analysis to detect high polysomy and amplification of MET gene may be useful in predicting shortened PFS and OS after Gefitinib treatment in lung adenocarcinoma." (PMID 25886066, 2015). "In this regard BCa is not similar to certain other cancers, such as gastric and lung adenocarcinomas, where frequent MET gene amplification leads to ligand-independent activation and enhanced sensitivity to Met inhibition." (PMID 25534569, 2014). "In another study with 183 lung adenocarcinomas, MET amplification was observed in 8 (4%) patients with wild-typed EGFR and wild-typed KRAS, indicating that the presence of MET gene amplification might be mutually exclusive with EGFR and KRAS mutations." (PMID 27234388, 2013). "Notably, some lung SCC samples exhibited mutations typically associated with lung adenocarcinoma or other non-squamous histology, such as KRAS, EGFR, and MET mutations." (PMID 41515905, 2025). "In contrast, the metastatic lung adenocarcinoma showed neoplastic cells with marked nuclear pleomorphism, intracytoplasmic eosinophilic hyaline globules, and TTF‐1 immunoreactivity, findings typically seen in lung adenocarcinoma with MET exon 14 skipping in an elderly female nonsmoker." (PMID 40028792, 2025). "Finally, the TCGA lung adenocarcinoma (LUAD) database was consulted to study the expression of ACE2 in EGFR- and KRAS-mutant samples and ACE2 expression was correlated with EGFR/HER, RAS, BRAF, ROS1, ALK, and MET mRNA expression." (PMID 36077610, 2022). "Moreover, LOC389641 may activate STAT3 signalling by increasing the expression of EGFR and MET and therefore downregulate cleaved-PARP to inhibit cell apoptosis in lung adenocarcinoma." (PMID 35379783, 2022). "To determine whether the MET-induced EGFR inhibition observed in lung tumors from EGFR/MET mice was clinically relevant, we performed a correlation analysis of pEGFR and pMET expression in a TCGA cohort of patients with lung adenocarcinoma." (PMID 34298655, 2021). "Additionally, our preclinical study suggested that BPI-9016M significantly inhibited tumor growth of lung adenocarcinoma with overexpression of c-MET, but not of those without c-MET overexpression." (PMID 31948451, 2020). "Current clinical approaches to overcome resistance in lung adenocarcinoma are the use of irreversible and mutant-selective EGFR inhibitors, and combining an EGFR inhibitor with a drug targeting a resistance pathway, such as the combination of erlotinib and an MET inhibitor." (PMID 26462152, 2015). "Lung adenocarcinoma subtypes 1–2 had the highest number of focal amplifications containing potential oncogenes (ERBB2, FGFR1, KRAS, MET), whereas LUAD-3 contained none." (PMID 33888829, 2021).
lung adenocarcinoma (continued). "As none of the selected cell lines including the two lung adenocarcinoma lines NCI-H1993 and NCI-H441 harbored an ALK rearrangement, inhibitor effects were expected to occur primarily due to c-MET inhibition." (PMID 33596971, 2021).
colorectal cancer (204 papers, 2005 to 2026). A primary or metastatic malignant neoplasm that affects the colon or rectum. "In colorectal cancer, treatment with cetuximab has been linked to increased MET amplification, a change associated with enhanced metastatic potential." (PMID 41123660, 2025). "In colorectal cancer liver metastasis, the emergence of CD4+FOXP3+ Tregs, coupled with elevated levels of α-smooth muscle Actin, HGF, and c-MET, suggests potential therapeutic targets for this metastatic variant of colorectal cancer." (PMID 39664377, 2024). "Downregulated miR-1 can cause tumor suppressor effects in colorectal cancer by the direct downregulation of the MET oncogene both at the RNA and the protein level." (PMID 25803870, 2015). "Although the MET p.T992I genetic mutation is commonly found in somatic colorectal cancer tissues, this is the first report also implicating this MET genetic mutation as a germline inherited risk factor for familial colorectal cancer." (PMID 21970370, 2011). "However, MET mutations are frequently detected in metastatic disease and increased expression/amplification of MET in colorectal cancer patients has been shown to promote the metastatic spread of cancer." (PMID 28420162, 2017). "While acquisition of novel mutations may be one of the possible explanations to this resistance in clinical treatment, activating mutations of several RTKs including ErbB2, ErbB3 and c-MET were discovered in human colorectal cancer and other cancers." (PMID 24205104, 2013). "Consequently, high expression of MET in colorectal cancers is linked to the development of distant metastases and represents a strong prognostic indicator for poor survival." (PMID 22251819, 2012). "Although, the MET p.T992I genetic mutation has been commonly found in somatic colorectal cancer tissues, this is the first report also implicating this MET genetic mutation as a germline inherited risk factor for familial colorectal cancer." (PMID 21970370, 2011). "Finally, the discovery that MET protein translation is impaired by miRNA, has led to the observation that loss of “tumor suppressor” miRNAs can cause MET overexpression during colorectal cancer progression." (PMID 22973229, 2012). "We further observed a significant increase in MET phosphorylation in tumor tissues compared with matched para-carcinoma tissues from patients with colorectal cancer." (PMID 41424360, 2026). "As treatments, it has been reported that the downregulation of HGF/MET signaling by siRNA of MET or the expression of HGF-antagonist has achieved the suppression of liver metastasis in colorectal cancer." (PMID 40076928, 2025). "MET amplifications have been shown to contribute to anti-EGFR resistance in colorectal cancer, and de novo amplifications are one of the major mechanisms of acquired resistance." (PMID 41590338, 2025). "In colorectal cancer, liver metastasis, CD4+FOXP3+ Tregs, and increased levels of α-smooth muscle actin, HGF, and c-MET indicate potential therapeutic targets for this metastatic form of colorectal cancer." (PMID 40281554, 2025). "MACC1 promotes the development of colorectal cancer by activating the HGF/c-MET signaling pathway, which is consistent with the high expression of MACC1 in our sequencing results." (PMID 40740230, 2025). "We previously found that dual c-MET/MEK1/2 inhibition attenuated RASMT colorectal cancer (CRC) xenograft growth." (PMID 40140597, 2025). "HSF4 binds to the MET promoter in colorectal carcinoma to enhance MET expression and promote tumor progression." (PMID 40004241, 2025). "Although the overall prevalence of MET amplifications in colorectal carcinoma is low (0.46%), it is enriched in ctDNA of patients with anti-EGFR refractory disease." (PMID 41590338, 2025). "HSF4 directly binds to the MET promoter and enhances its expression, thereby promoting tumor progression in colorectal carcinoma." (PMID 40004241, 2025).
colorectal cancer (continued). "Specifically, strong evidence points to the involvement of sorting nexins (SNXs), particularly SNX1 and SNX2, in the signaling and trafficking of the receptor tyrosine kinase (RTK) MET in colorectal cancer (CRC)." (PMID 38836326, 2024). "It regulated cell survival, proliferation, and migration through increased MET protein stability in colorectal cancer." (PMID 37328854, 2023). "MET amplification has been detected after anti‐EGFR antibody treatment of KRAS‐wild‐type colorectal cancer." (PMID 36416133, 2023). "The MET gene facilitates tumor invasion and metastasis in colorectal cancer, and gains of the MET gene, which corresponds with chromosome 7q31, also confer poor prognosis." (PMID 35565354, 2022). "In colorectal cancer, loss of ARID1A located at enhancers leads to dramatic changes in chromatin accessibility, and influences the expression of MET in colorectal cancer cell growth and adhesion." (PMID 33125076, 2021). "Herein, we used a multiomics data analysis to evaluate the predictive and prognostic roles of genetic and epigenetic modulation of c-MET (hepatocyte growth factor receptor)/epidermal growth factor receptor (EGFR) in colorectal cancer (CRC)." (PMID 34512327, 2021). "We found that c-MET expression is higher (p = 1.24e-07) while EGFR expression is lower (p = 4.67e-04) in colorectal cancer cohorts compared to adjacent normal cohorts." (PMID 34512327, 2021). "MET- and Wnt pathway activation are also both prominently involved in colorectal cancer (CRC) progression." (PMID 34590584, 2021). "Overall, the staining intensity score for c-MET was relatively similar across three of the cancer types (lung, genitourinary and breast), with a slight decrease in intensity for colorectal cancer." (PMID 33437521, 2020). "This corresponds to other data showing that lung and colorectal cancer cells with resistance to EGFR-related TKIs displayed a rebound effect in cell proliferation after the treatment with anti-MET TKIs was interrupted." (PMID 31546690, 2019). "In brief, our results showed that CC-CAFs promoted metastasis of colorectal cancer by up-regulation of CD44 through HGF/MET/AKT signal." (PMID 31367190, 2019). "In a 3D culture system of colorectal cancer cells, the phosphorylation of MET and RON was higher in cells with weaker response to EGFR-directed antibody cetuximab." (PMID 31557260, 2019). "Recent evidence showed how combined analysis of KRAS and PIK3CA mutations, MET and PTEN expression in primary tumors and corresponding metastases in colorectal cancer demonstrated discordance between the two sites." (PMID 30282914, 2018). "The authors suggest that combination therapies of ADAM17 and c-MET inhibitors would be more clinically effective in KRAS mutant colorectal cancer." (PMID 29230082, 2017). "ADAM17 was shown to negatively regulate c-MET signaling by increasing the levels of soluble MET in a KRAS mutant colorectal cancer model." (PMID 29230082, 2017). "The purpose of this study was to explore gene copy number (GCN) variation of EGFR, HER2, c-MYC, and MET in patients with primary colorectal cancer (CRC)." (PMID 28764718, 2017). "As other pathway, Liska and colleague have reported that hepatocyte growth factor (HGF)-activating c-MET rescued EGFR inhibition in colorectal cancer cells." (PMID 28642617, 2017). "In this study, we analysed GCN variation of the EGFR, HER2, c-MYC, and MET genes in 334 colorectal cancer tissue samples using silver-enhanced in situ hybridization (SISH)." (PMID 28764718, 2017). "A few recent works showed that specific repetitive sequences (i.e. LINE-1) residing within some proto-oncogenes lead to the increased expression of oncogenes such as MET in colorectal cancer." (PMID 27016420, 2016). "A complex of MET, CD44 variant 6 and the MET ligand HGF has been identified in the colorectal cancer cell line HT-29 and has been demonstrated as being essential for MET activation." (PMID 26243458, 2016).
colorectal cancer (continued). "It should be mentioned though that in colorectal cancer, miR-133b has been shown to block cell proliferation by directly targeting the c-MET protein." (PMID 25743594, 2015). "By using colonic fibroblast cell line CCD-18co and chemotherapy drug CPT-11, we demonstrate that fibroblasts play a functional role in chemoresistance of colorectal cancer cells presumably through fibroblast-derived HGF in tumors via c-MET signaling." (PMID 26090722, 2015). "In our in vivo models, the combination of CPT-11 with anti-HGF antibody showed a potent anti-cancer effect on human colorectal cancer, as evidenced by the strong inhibition of tumor growth and interference with c-MET signal transduction." (PMID 26090722, 2015). "EGFR immunoprecipitated together with MET in cetuximab-resistant colorectal cancer cells, and this interaction was also observed in parental cells by TGFα stimulation." (PMID 26318427, 2015). "miR-1 has tumor suppressor functions in colorectal cancer by directly downregulating MET oncogene both at RNA and protein level." (PMID 24949449, 2014). "Based on the evidence that c-MET is a target gene of MACC1 in colorectal cancer, the c-MET promoter fragments between −223 and +60 were amplified and cloned into a pGL3-basic vector, which is a positive regulatory element." (PMID 25009663, 2014). "In the present study, we not only confirmed the over-expression of c-MET, ErbB2 and ErbB3 in human colorectal cancer, but also revealed the variation and complementary of these receptors." (PMID 24205104, 2013). "MET exons were amplified by PCR from germline DNA of 148 affected sibling pairs with colorectal cancer." (PMID 21970370, 2011). "Tumour cells with high c-MET expression are specifically enriched at the invasive front of colorectal carcinomas, where they mediate EMT, migration and matrix invasion." (PMID 22110593, 2011). "Furthermore, the CD44v6-interfering peptide or VFF18 were also reported to block ligand-dependent activation of c-MET and subsequent colorectal cancer cell scattering and migration." (PMID 41369362, 2025). "The MEK and MET Inhibition in Colorectal Cancer (MErCuRIC) study aimed to investigate the MTD, RP2D and safety/tolerability during the dose escalation, and evaluate preliminary anti-tumour activity of combined binimetinib/crizotinib treatment in RASMT CRC patients in the phase Ib study." (PMID 40211189, 2025). "Because we and others have ever found that GALNT2 could regulate EGFR and MET phosphorylation which have been demonstrated to modulate colorectal cancer metastasis, we tested if GALNT2 knockout could interfere with their signaling." (PMID 36409270, 2023). "MET amplification and fusion occurred concurrently in patients with colorectal cancer and CCC." (PMID 36483096, 2022). "HGF could activate ERK1/2 and AKT via MET phosphorylation, resulting in cetuximab resistance in colorectal cancer patients." (PMID 35204406, 2022). "For example, in colorectal cancer with liver metastasis, miR-31-5p may inhibit and support EMT by upregulating c-MET, and the downregulation of miR-200 in colorectal cancer increases the expression of ZEB1, thereby promoting EMT." (PMID 36093435, 2022). "For further comparison, increased MET gene CN measured by fluorescence in situ hybridization was found in 1 to 4% of tumors from NSCLCs, 8.5% of lung sarcomatoid carcinomas, and 4.2% of colorectal cancer tissue samples." (PMID 33596971, 2021). "For example, stimulation of hepatocyte growth factor (HGF) in colorectal cancer cells (CRCs) promotes phosphorylation of β-catenin in tyrosine residue and its dissociation from Met (HGFR is encoded by proto-oncogene MET) and thus upregulates β-catenin expression via the PI3-K pathway." (PMID 31921137, 2019). "Growing data suggest suppression of c-MET activation may inhibit tumor activity for patients with colorectal carcinoma." (PMID 30360560, 2018).